EGFR (epidermal growth factor receptor)
Diseases named in the same sentence as EGFR in open-access papers (continued):
Sharing a sentence is not in itself a finding about the gene and the disease.
cancer (continued). "Therapeutic blocking antibodies, such as those targeting HER2 and EGFR, have emerged as an important new treatment option in the clinic for carcinomas of the breast, lung and colon." (PMID 25340344, 2014). "We next performed the assay using A431 cells (a human epithelial carcinoma cell line that overexpresses EGFR) as target cells and two anti-EGFR mAbs, cetuximab and panitumumab." (PMID 24752341, 2014). "We used COS-7 cells naturally expressing endogenous EGF receptors, in order to ensure that the monomer/dimer equilibrium was unaltered, in contrast to A431 carcinoma cells or EGFR-transfected fibroblasts." (PMID 25265278, 2014). "Respiratory side effects in the treatment of human carcinomas due to off-target inhibition have been described for the EGFR kinase inhibitor gefitinib (Iressa), limiting the therapeutic benefit of this drug." (PMID 24438162, 2014). "The irreversible ErbB family receptor blocker, afatinib (BIBW 2992), which inhibits EGFR, HER2 and HER4 tyrosine kinases, has been shown to be effective in the elimination of cancer cells with HER2 gene mutations in cell lines and animal models." (PMID 24137465, 2013). "A fascinating example of the link between alternative splicing and signalling cascades has been recently provided by studying the metabolic effects, increased glucose uptake and lactate production, of EGFR activation in human cancer cells." (PMID 24078813, 2013). "In cancer cells two cell signalling pathways, the epidermal growth factor receptor (EGFR) and the insulin-like growth factor receptor 1 (IGF1-R) signalling, have been reported to be responsible for proliferation inhibition upon miR-7 induction." (PMID 23762407, 2013). "Another therapy utilized an EGFR (epidermal growth factor receptor) antagonist, which prevented promotion of Akt survival signaling and inhibited cancer cell proliferation." (PMID 24688727, 2013). "Our pharmacokinetic modeling suggests that for part of each day drug levels fell below the IC50 of 3 μg/ml defined for phospho-ERK (downstream effector of EGFR) in a xenograft cancer model." (PMID 23638043, 2013). "Since nimotuzumab is an approved anti-EGFR mAb for therapeutic use in cancer treatment, exploring the precise anticancer mechanisms of nimotuzumab will help increase the efficacy of this agent in clinical practice." (PMID 23976954, 2013). "EGFR is overexpressed in many types of cancers, especially CRC, and the overexpression seems to reflect more aggressive histological and clinical behaviors." (PMID 23865079, 2013). "Monoclonal antibody (mAb) has fulfilled the promise of being the “Magic Bullet” in oncology with the clinical success of mAbs against CD20, Her-2/neu, epidermal growth factor receptor, vascular endothelial cell growth factor and others in a variety of cancers." (PMID 23425356, 2013). "The role of EGFR in the pathogenesis and progression of various malignant tumors has been extensively investigated." (PMID 23637996, 2013). "Epidermal growth factor receptor tyrosine kinase inhibitors (EGFR-TKIs) such as gefitinib represent another strategy for EGFR-targeted cancer therapy." (PMID 23748900, 2013). "For example, the EGFR-binding Z domain was employed as homing device for the delivery of therapeutic agents towards a wide range of EGFR-overexpressing cancer cells." (PMID 24564841, 2013). "The epidermal growth factor receptor (EGFR) plays an essential role during development and diseases including cancer." (PMID 24076656, 2013). "As demonstrated in pre-clinical studies, prolonged exposure of cancer cells to EGFR-blocking antibodies gives rise to resistant cells that have increased VEGF expression." (PMID 23420587, 2013).
cancer (continued). "Lapatinib is a tyrosin kinase inhibitor of EGFR and blocks EGFR downstream signaling in cancer cell." (PMID 24039841, 2013). "In vitro radiosensitivity experiments were employed to determine the ability of miR-7 to reverse the radioresistance conferred on human cancer cells by EGFR." (PMID 24349829, 2013). "Conversely, in MCF-7 cells, EGFR phosphorylation was lower than the control suggesting that endogenous EGFR phosphorylation is relatively higher in comparison to other cancer cells." (PMID 24059654, 2013). "In many cancers, EGFR evades degradation by entering the recycling pathway, and this invites a role for PKC and the pericentrion in these EGF-induced oncogenic properties." (PMID 24244711, 2013). "In wound healing, for development of cancer metastasis or for spreading of cells on the implant surfaces adhesion molecules, as integrins, cadherins, the epidermal growth factor receptor (EGFR), are of importance." (PMID 23936843, 2013). "As the leading cause of cancer mortality worldwide, 50-80% of non-small cell lung cancer (NSCLC) is associated with EGFR overexpression; with 65% of them also found to have an increased EGFR gene copy number." (PMID 24252457, 2013). "The ErbB receptor family, including EGFR, is important in cancer development and these family members are over expressed in various cancers including CRC." (PMID 23675573, 2013). "Overall, these results suggest that EGFR is also a downstream element in the Shh signaling pathway in HeLa cancer cells." (PMID 24133411, 2013). "The HER family (Human Epidermal growth factor Receptor, also known as the ErbB family) of cell surface receptors plays critical roles in normal cell physiology, development, and cancer pathophysiology." (PMID 23990774, 2013). "Ligands of EGFR have been shown to be secreted by different types of cancer cells following IR, resulting in the autocrine activation of the EGFR/Ras/MEK/MAPK pathways which can protect irradiated cells from IR-induced death." (PMID 23588995, 2013). "The identification of Src and EGFR, and the subsequent extensive investigations of these proteins have long provided cutting edge research in cancer and other molecular and cellular biological studies." (PMID 23702846, 2013). "On the basis of these findings, other preclinical studies examined the possibility of restoring apoptosis treating cancer cells with an anti-EGFR antibody that consequently decreased NF-κB activity." (PMID 24340014, 2013). "The induction of stable disease with EGFR-targeted therapy is due, at least partially, to reversal of the malignant phenotype of cancer stem cells and inhibition of the epithelial-to-mesenchymal transition." (PMID 23637683, 2013). "It inhibits cancer cell growth by targeting EGFR and thus downregulating its downstream pathway members." (PMID 23555785, 2013). "It is well-established that EGFR and c-Src tyrosine kinase are co-overexpressed in human cancers, and experimental modeling of their co-overexpression in untransformed hMECs in the laboratory leads to their collaborative promotion of oncogenesis." (PMID 23637902, 2013). "Phosphorylation of EGFR is studied for cancer therapy because EGFR regulates many cellular processes including cell proliferation, differentiation, and survival." (PMID 23706036, 2013). "A number of studies investigated the cross talk between MET and EGFR demonstrating its contribution to cancer growth, migration and invasion." (PMID 24167634, 2013). "The proportion of cases with high EGFR expression increases according to the stage of the cancer, and high EGFR expression is related to poor prognoses in some types of cancers." (PMID 23577026, 2013). "Constitutively activated oncogenic signaling via genetic mutations such as in the EGFR/PI3K/Akt and Ras/RAF/MEK pathways has been recognized as a major driver for tumorigenesis in most cancers." (PMID 24217114, 2013).
cancer (continued). "For instance, upregulation of insulin-like growth factor receptor (IGF1R), seen in subnetwork 3, has been identified in a wide variety of human cancers, and in vitro evidence suggests that this upregulation contributes to resistance against EGFR inhibitors." (PMID 24068912, 2013). "It is important to stress that although HT-29 and COLO205 cells are popular in cancer research, in addition to their different EGFR expression, they also are heterogeneous in a variety of other cellular properties." (PMID 23857061, 2013). "More specifically RHAMM interacts with ERK increasing the proliferative ability of these cancer cells through a mechanism that involves the interaction of CD44 with the epidermal growth factor receptor (EGFR)." (PMID 24083250, 2013). "In an effort to develop new cancer diagnostic agents, several PET and SPECT ligands have been synthesized and evaluated for imaging of EGFR-TK." (PMID 23494210, 2013). "Our previous study demonstrated that, in patients with NSCLC, HGF is primarily detected in cancer cells with acquired resistance to EGFR-TKIs, suggesting that the production of HGF by these cells occurs mainly via an autocrine mechanism." (PMID 23690929, 2013). "The early and sensitive detection of HCC based on molecular cancer markers, such as EGFR, is a critical step in improving the currently dismal prognosis of HCC patients." (PMID 23710458, 2013). "A peculiar feature of basal-like/triple-negative tumors is the over-expression of epidermal growth factor receptor (EGFR), a receptor which plays a pivotal role in cancer development." (PMID 24260469, 2013). "Upon binding to the EGFR, receptor-mediated endocytosis and transport to the cytosol of EGF occurs suggesting that the EGFR denotes an excellent target for drug delivery to EGFR overexpressing cancer cells in GBM." (PMID 24175095, 2013). "Overexpression of EGFR, HER2 and HER3 is associated with decreased survival in cancer, while HER4 overexpression is correlated with increased survival." (PMID 23990774, 2013). "In our study, comparison of EML4-ALK fusion status with the presence of EGFR and KRAS mutations in the same cancer samples revealed that EML4-ALK fusions occurred in the absence of EGFR or KRAS mutations." (PMID 23341890, 2013). "The first fluidic chamber was densely packed with microbeads that are functionalised with target-specific antibodies (e.g. EGFR) so as to capture cancer-MVs." (PMID 26082317, 2013). "Radiation induces an increase in the EGFR expression in cancer cells, and blockade of EGFR signaling sensitizes cells to the effects of radiation." (PMID 24053278, 2013). "EGFR activated signaling pathways control cell proliferation, apoptosis, angiogenesis and metastatic spread in several different human cancers." (PMID 24132149, 2013). "Patients with EGFR wild-type cancers treated with erlotinib also experience improved progression-free survival and overall survival in the maintenance setting and additional biomarkers are needed for clinical decision making." (PMID 24100924, 2013). "As mentioned in previous sections, EGFR transactivation in response to the stimulation of PARs occurs in a large number of cancers and is believed to contribute to cancer development and progression." (PMID 24215724, 2013). "EGFR has been intensively studied, principally due to its participation in controlling fundamental cellular functions and its role in cancer development." (PMID 24349439, 2013). "In the present study, both temsirolimus and everolimus partially suppressed the phosphorylation of p70S6K and 4E-BP1, as well as inhibited the survival of EGFR mutant cancer cells in vitro." (PMID 23690929, 2013). "Intracellular communication between EGFR and Src, which contributes to cancer malignancy, was first demonstrated in the late 1980s." (PMID 23702846, 2013). "Some of these antibodies have been humanized and used to treat cancers expressing high levels of EGFR." (PMID 23894364, 2013).
cancer (continued). "It is well documented that miR-7 plays critical roles in the downregulation of EGFR expression in many cancer types." (PMID 23840262, 2013). "These monoclonal antibodies, chimeric and humanized, bind to the EGFR, preventing activation of the EGFR downstream signaling pathways, which are important for cancer cell proliferation, invasion, metastasis, and neo-vascularization." (PMID 23437064, 2013). "The present data have shown that PKG II inhibits EGF/EGFR-induced proliferation and migration and associated signal transduction of MAPK-mediated pathways of cancer cells." (PMID 24273605, 2013). "Tyrosine kinase inhibitors targeted against the EGFR, which block tyrosine kinase phosphorylation, have been shown to inhibit the EGFR-mediated proliferation of EGFR-rich cancer cells." (PMID 24137317, 2013). "The ability of EGFR activation to modulate the metabolism of cancer cells requires the expression of the PKM2 splicing isoform of pyruvate kinase M (PKM), the enzyme that catalyzes the final step of glycolysis." (PMID 24078813, 2013). "Due to their multidimensional role in the progression of cancer, EGFR and its family members have emerged as attractive candidates for anticancer therapy." (PMID 24312376, 2013). "Studies investigating the TGFα-EGFR signaling pathways that promote the growth and spread of cancer cells." (PMID 23986907, 2013). "In the present study, we attempted to determine how EGFR-TKI treatment in cancer cells induced interstitial pneumonia." (PMID 23592411, 2013). "Accumulating evidence of the functional impact of nEGFR demonstrates a need to understand the extent to which this protein contributes to cancer growth and progression as well as to the therapeutic response to EGFR-targeted therapies." (PMID 23593472, 2013). "EGFR-TK activation is involved in the proliferation, invasion, metastasis, angiogenesis, and suppression of apoptosis of cancer cells." (PMID 23494210, 2013). "EGF-stimulated EGFR phosphorylation promotes cancer cell proliferation through the downstream phosphoinositide 3-kinase (PI3K)/Akt and extracellular signal-regulated kinase (ERK1/2) pathways." (PMID 23566546, 2013). "EGFR targeted therapies combined with radiotherapy has been regarded as a very potential strategy for treatment of some cancers of epithelial origin." (PMID 23976954, 2013). "Src also participates in cancer cell functions involving the other family member of the EGFR and/or its phosphorylation on a tyrosine residue that is analogous to the EGFR Y845." (PMID 23702846, 2013). "We next investigated Mig6 expression, EGFR expression and EGFR activity in panels of cancer cell lines." (PMID 23935914, 2013). "When the cancer cells overexpressing EGFR were exposed to radiation, the survival and proliferation mechanisms were predominantly activated through signaling via PI3K-Akt and Ras-Erk." (PMID 24053278, 2013). "Over-expression of EGFR and COX-2 and the interaction between EGFR signaling and COX-2 activity have been implicated as causative factors for cancer." (PMID 24155892, 2013). "EGFR (epidermal growth factor receptor) expression, which is often dysregulated in many human cancers, was decreased with fucoxanthin." (PMID 24351910, 2013). "The Epidermal Growth Factor Receptor (EGFR) on the cancer cell surface relays signals of proliferation, angiogenesis, metastasis and antibodies binding it have been partly responsible for the observed outcomes improvement." (PMID 23374602, 2013). "Further investigations are needed to clarify how EGFR-TKI regulates IL-6 production in cancer cells." (PMID 23592411, 2013). "The question on which subset of cancer patients would be most benefited from these treatments is still under debate, and meanwhile the use of EGFR-targeted therapies in advanced cancer patients remains largely empirical." (PMID 23637683, 2013). "EGFR also plays an important role in regulating cell proliferation and resistance to cell apoptosis during cancer development." (PMID 24321281, 2013).
cancer (continued). "Flow cytometry analyses have shown that the combination of bufalin and gefitinib induced apoptosis of HCC827 cells, although HGF rendered EGFR mutant cancer cells resistance to apoptosis induced by EGFR-TKIs." (PMID 23533466, 2013). "In contrast, low levels of EGFR expression were seen in GBM4 GBM-derived cancer stem-like cell line, and this observation is also consistent with microarray-based comparative genomic hybridization data obtained from colleagues." (PMID 23555046, 2013). "Results from a large body of preclinical studies and clinical trials suggest that targeting EGFR represents a significant contribution to cancer therapy." (PMID 23409107, 2013). "Elevated levels of epidermal growth factor receptor (EGFR), or increased expression of the EGFR gene, have been reported in a number of human cancers of epithelial origin, including head and neck, thyroid, breast, and colon cancers." (PMID 24131756, 2013). "Epidermal growth factor receptor is a transmembrane receptor tyrosine kinase that controls cellular pathways crucial in cancer development, growth, invasion, metastasis, and angiogenesis." (PMID 23970998, 2013). "In summary, we showed that the anti-EGFR mAb nimotuzumab radiosensitizes cancer cells by inducing more apoptosis and unrepaired DSBs." (PMID 23976954, 2013). "The results confirmed that PKG II inhibited EGF-induced activation of Ras protein and MAPK/ERK in AGS cells, suggesting that PKG II also inhibited EGF/EGFR-induced signal transduction of MAPK/ERK-mediated pathway in this cancer cell line." (PMID 23613900, 2013). "Our results provide direct evidence for a possible additional mechanism, i.e clustering per se, for the ligand free activation of EGFR in cancer cells expressing high levels of the wild-type receptor." (PMID 23894364, 2013). "Taken together, these results suggest that the EGFR/ERK pathway has a potential role in the regulation of Mcl-1 protein levels in cancer cells of the BL subtype of TNBC." (PMID 23601074, 2013). "EGFR phosphorylation plays a key role in modulating the activation of signaling pathways related to cancer progression." (PMID 23520446, 2013). "It strongly suggests that PKG II is a potential endogenous EGFR inhibitor and will provide new hint on strategy of cancer therapy." (PMID 23613900, 2013). "Les anticorps monoclonaux et les inhibiteurs de petites molécules de l′EGFR sont actuellement évalués chez les patients atteints de cancer du poumon." (PMID 23734272, 2013). "In this study EGFR, a putative target gene for miR-574-3p, was up-regulated in PCa and increased in advanced cancer." (PMID 23554959, 2013). "EGFR is also involved in various cancers by contributing to malignancy due to over-expression or oncogenic mutations." (PMID 24349439, 2013). "EGFR inhibition has been shown to sensitize malignant tumors to chemotherapy with cisplatin or carboplatin, while combining EGFR inhibition with PARP inhibition has also produced encouraging findings." (PMID 24244833, 2013). "Selective small molecule tyrosine kinase inhibitors (TKIs) of EGFR, such as gefitinib and erlotinib, were among the first targeted therapies developed for cancer." (PMID 23935914, 2013). "Based on the appreciation of the role of EGFR in cancer, several molecularly targeted agents such as gefitinib, erlotinib, and cetuximab (Erbitux, C225) have been developed to inhibit the activity of this receptor." (PMID 24053278, 2013). "For example, the “Cancer, Cellular Movement, Cellular Growth and Proliferation” network encompasses EGFR, FGFR2 and other key genes, such as AURKA, a cell cycle checkpoint mediator, and SPP1, LAMA3 and GJA1, which play a role in cell communication." (PMID 23383013, 2013). "EGFR activation and/or overexpression often leads to signal transduction cascades, which in turn contribute to cell proliferation, angiogenesis, cancer invasion and metastasis." (PMID 24137392, 2013).